GABRD (gamma-aminobutyric acid type A receptor subunit delta)
Description:
Delta subunit of the heteropentameric ligand-gated chloride channel gated by gamma-aminobutyric acid (GABA), a major inhibitory neurotransmitter in the brain. GABA-gated chloride channels, also named GABA(A) receptors (GABAAR), consist of five subunits arranged around a central pore and contain GABA active binding site(s) located at the alpha and beta subunit interface(s). When activated by GABA, GABAARs selectively allow the flow of chloride anions across the cell membrane down their electrochemical gradient. GABAARs containing delta/GABRD subunits are predominantly located in extrasynaptic or perisynaptic positions on hippocampus and cerebellar granule cells, and contribute to the tonic GABAergic inhibition (By similarity). GABAAR containing alpha-4-beta-3-delta subunits can simultaneously bind GABA and histamine where histamine binds at the interface of two neighboring beta subunits, which may be involved in the regulation of sleep and wakefulness.
Synonyms: GABAARdelta; EIG10; EJM7; GEFSP5
Tractability: Small molecule: an approved drug acts on it; a structure with a bound ligand is known; a high-quality ligand is known; it belongs to a druggable protein family. Antibody: its Gene Ontology location is reachable by antibodies, with high confidence; UniProt places it where antibodies can reach, with medium confidence; UniProt predicts a signal peptide or a membrane-spanning region. PROTAC: ubiquitination databases record sites on it; a small molecule that binds it is known.
Target class: Ion channel; GABA-A receptor; Ligand-gated ion channel
Gene: Protein-coding gene on chromosome 1 (2,019,329 to 2,030,758, forward strand). Ensembl gene ENSG00000187730.
Subcellular location: Cell membrane
Subcellular location (Human Protein Atlas): Golgi apparatus; Vesicles
Gene Ontology:
Molecular function: protein binding; GABA-A receptor activity; extracellular ligand-gated monoatomic ion channel activity; monoatomic ion channel activity; transmembrane signaling receptor activity; transmitter-gated monoatomic ion channel activity involved in regulation of postsynaptic membrane potential
Biological process: chloride transmembrane transport; gamma-aminobutyric acid signaling pathway; extrasynaptic signaling via GABA; signal transduction; synaptic transmission, GABAergic; chemical synaptic transmission; monoatomic ion transmembrane transport; monoatomic ion transport; regulation of postsynaptic membrane potential
Cellular component: GABA-A receptor complex; GABA-ergic synapse; plasma membrane; axon; dendrite; glutamatergic synapse; membrane; neuronal cell body; postsynaptic membrane
Genetic constraint (gnomAD): Loss-of-function variants: 24 observed, 42.96 expected, observed/expected ratio (o/e) 0.56, 90% interval 0.4 to 0.79. The upper end of that interval is the gene's LOEUF score, 0.79, which puts it in group 3 of 6, group 1 being the genes least tolerant of losing a copy. Missense variants: 495 observed, 609.19 expected, observed/expected ratio (o/e) 0.81, 90% interval 0.75 to 0.88. Synonymous variants: 313 observed, 265.77 expected, observed/expected ratio (o/e) 1.18, 90% interval 1.07 to 1.29.
Gene-disease validity (ClinGen):
ClinGen rates the evidence that GABRD causes each of these diseases.
complex neurodevelopmental disorder (autosomal dominant): Moderate. A disorder that involves more than one phenotype associated with the central nervous system, including but not limited to intellectual disability, autism, and seizures (epilepsy).
epilepsy (autosomal dominant): Limited. A brain disorder characterized by episodes of abnormally increased neuronal discharge resulting in transient episodes of sensory or motor neurological dysfunction, or psychic dysfunction.
Homologues: Orthologues: macaque GABRD (96% identical), rat Gabrd (92% identical), guinea pig GABRD (92% identical), mouse Gabrd (92% identical), dog GABRD (91% identical), chimpanzee GABRD (79% identical), pig GABRD (76% identical), zebrafish gabrd (75% identical), tropical clawed frog gabrd (69% identical). Paralogues in human: GABRB1 (40% identical), GABRB3 (39% identical), GABRB2 (39% identical), GABRP (38% identical), GABRQ (36% identical), GLRA2 (35% identical), GLRA1 (34% identical), GLRA3 (34% identical), GABRG2 (33% identical), GABRR2 (33% identical), GABRR1 (32% identical), GABRR3 (31% identical), and 33 more.
Diseases named in the same sentence as GABRD in open-access papers:
GABRD is named in the same sentence as 59 diseases in open-access papers, as found by Europe PMC text mining. Sharing a sentence is not in itself a finding about the gene and the disease. The quoted sentences say what the papers report.
epilepsy (12 papers, 2008 to 2025). "Nine genes, two of which are human epilepsy-associated genes (GABRD and CHRNA2), had markers with heterozygosities falling below the 0.3 cut-off, prohibiting the drawing of conclusions about these genes." (PMID 21518446, 2011). "However, no replication of GABRD mutations in JME patients have been reported since 2004, but a more recent study identified several gain-of-function variants in GABRD in patients with neurodevelopmental disorders and epilepsy." (PMID 40564020, 2025). "In addition, mutations in GABRD are thought to be related to the pathology of epilepsy." (PMID 33551813, 2020). "A different group of patients, those with GABRD (GABAAR δ subunit gene) gain-of-function mutations, also exhibit neurodevelopmental disorders and epilepsy, including absence seizures in early childhood." (PMID 40956609, 2025). "Genes potentially associated with FS-related epilepsy include SCN1A, ADGRV1, SCN1B, SCN9A, GABRG2, GABRD, and CPA6." (PMID 35813073, 2022). "They found an enrichment of rare non-coding CNVs near known epilepsy genes, with the GABRD gene showing the strongest and only nominally significant association with 4 non-coding deletions amongst the epilepsy patients." (PMID 34663447, 2021). "For example, the following genes were previously thought to be associated with epilepsy: EFHC1, SCN9A, CLCN2, GABRD, SRPX2 and CACNA1H." (PMID 28558813, 2017). "GABRD (gamma‐aminobutyric acid type A receptor subunit delta) (1p36.33) mediates neuronal inhibition through GABA‐A receptor binding and is implicated in Akt signaling, chloride channel activity, and epilepsy." (PMID 40631452, 2025). "An epilepsy candidate gene KCNAB2 was found to be deleted in the majority of seizure prone 1p36 patients, and human gamma-aminobutyric acid A receptor delta-subunit gene (GABRD) has been implicated in abnormal neurodevelopment." (PMID 19019217, 2008). "This breed had the lowest overall average heterozygosity and results for eleven genes, three of which are human epilepsy-associated (GABRD, KCNA1, and ME2), could not be determined due to low heterozygosity." (PMID 21518446, 2011). "Five out of 10 patients with deletions including both GABRD and KCNAB2 had epilepsy in our cohort." (PMID 36369750, 2023). "Interestingly, our findings suggested that GABRD were up-regulated in the glioma tissue of patients with glioma-associated epilepsy compared with those in non-epileptic patients, indicating that SAPs may linked to the pathogenesis of seizures in glioma patients." (PMID 33969375, 2021).
glioma (8 papers, 2020 to 2024). A benign or malignant brain and spinal cord tumor that arises from glial cells (astrocytes, oligodendrocytes, ependymal cells). "It is possible that Cg13916816 is an important CpG site that influences GABRD expression in IDH wild-type low-grade gliomas." (PMID 37181811, 2023). "However, GABRD was upregulated in low-grade glioma patients with seizures, reinforcing the link already described for glutamate receptors between synapses, gliomagenesis and the pathogenesis of seizures." (PMID 37511496, 2023). "On the contrary, GABRD were down-regulated in glioma tissue." (PMID 33969375, 2021). "However, in low-grade gliomas, there are reports claiming that GABRD can be a prognostic marker, and patients with low GABRD expression often have a poor prognosis." (PMID 34194536, 2021). "In another TCGA-based bioinformatic study, GABRD expression was significantly decreased in IDH wild-type diffuse low-grade gliomas compared with that in IDH mutant tumors, while patients with a high expression of GABRD had better prognosis than those with a low expression of GABRD." (PMID 33336074, 2020). "In addition, GABRD and SYT1 are implicated in gliomagenesis, and all other core genes, with the exception of OPALIN, have been reported to play a role in tumor-related diseases, including glioma." (PMID 33718116, 2020). "Four SAPs, GRIK2, GABRD, GRID2 and ARC, made up a signature correlated with a positive prognostic value for patients affected by low-grade gliomas." (PMID 37511496, 2023). "Among the core genes, the expression levels of GABRD and SYT1 were closely related to the survival time of glioma patients." (PMID 33718116, 2020). "Interestingly, we found that GABRD were up-regulated in LGG patients with seizures, indicating that SAPs may link to the pathogenesis of seizures in glioma patients." (PMID 33969375, 2021). "Among the 10 candidates, high mRNA expression of CCL8, FCGR2B, and TUBA4A and low mRNA expression of GABRD, PRAME, and SYN1 were significantly correlated with worse prognosis, while the mRNA expression of CCL18, SCN1B, SNCB, and VSNL1 showed no connection to the overall survival of glioma patients." (PMID 36685974, 2022).
colon cancer (6 papers, 2021 to 2025). "Given that GABRD is associated with poor prognosis in colon cancer, we examined the expression of this particular GABAA receptor subunit over time in the AOM mouse model." (PMID 38886975, 2024). "GABRD is widely reported to be closely associated with colon cancer." (PMID 35721115, 2022). "Given this, it was suggested that GABRD may be associated with the malignant progression of colon cancer." (PMID 34194536, 2021). "However, there were studies which constructed predictive models for prognostic risk using data of colon cancer patients and found that lowly expressed GABRD is remarkably associated with good overall survival (OS)." (PMID 34194536, 2021). "This concurs with our observation that GABRD expression is increased in colon cancer and correlates with poor clinical outcome." (PMID 38886975, 2024). "To explore potential colon cancer risk-related genes, we compared the expression of 11 RRGs in normal and tumor tissues and found that PANX2 and GABRD are highly expressed in tumors, while PPARGC1A is less expressed in tumors." (PMID 37020539, 2023). "Overall, in this study, the potential role and prognostic ability of GABRD in colon cancer were explored through data mining, which can be a clue for further research on GABRD." (PMID 34194536, 2021). "LinkedOmics was used to screen out the differentially expressed genes related to GABRD expression in colon cancer." (PMID 34194536, 2021). "Kaplan-Meier analysis suggested that the upregulation of GABRD expression was related to the poor prognosis of patients with colon cancer." (PMID 34194536, 2021). "The potential regulatory mechanism in cancer was then explored, thus offering a deeper understanding of the relationship between GABRD and colon cancer." (PMID 34194536, 2021). "In general, in this research, by mining the colon cancer dataset in the Oncomine database, it was uncovered that GABRD expression was higher in colon cancer tissue compared with that in normal tissue." (PMID 34194536, 2021). "It was indicated that GABRD was likely to be regulated by these networks or play a role in colon cancer through these target networks." (PMID 34194536, 2021). "At the same time, after the patients were divided according to the N stage and cancer stage, each subgroup exhibited an increasing trend toward GABRD expression with the progression of colon cancer." (PMID 34194536, 2021). "Then, it was also found that the expression of GABRD in each subgroup of colon cancer tissue was all high compared with that in normal tissue." (PMID 34194536, 2021). "This also provides support for GABRD to become a prognostic marker for colon cancer patients, as well as offers clues for further research on relevant functional mechanisms." (PMID 34194536, 2021). "In this study, the Oncomine database was used for expression analysis, and it was found that the expression level of gamma-aminobutyric acid type A receptor subunit delta (GABRD) gene was upregulated in colon cancer tissue compared with that in normal tissue." (PMID 34194536, 2021). "Then, in this research, the GSEA tool of LinkedOmics was applied to perform enrichment analysis on kinase targets, miRNA targets, and transcription factor targets, and the possible target networks of GABRD in colon cancer were obtained." (PMID 34194536, 2021). "Also, a report claimed that the high expression of GABRD mRNA can promote the progression of colon cancer to advanced TNM stages." (PMID 34194536, 2021). "In order to further understand the possible role of GABRD in colon cancer, enrichment analysis was carried out on kinase, miRNA, and transcription factor targets of GABRD using the GSEA tool of LinkedOmics (FDR < 0.25), and target regulatory networks related to GABRD were mined." (PMID 34194536, 2021). "Finally, websites like GEPIA were used to detect the predictive ability of GABRD on the prognosis of patients with colon cancer." (PMID 34194536, 2021).
colon cancer (continued). "By using the GEPIA tool, KM analysis was conducted to detect the relationship between GABRD expression and prognosis of colon cancer patients, and the results manifested that the OS rate of patients in the GABRD low-expression group was significantly higher than that in the high-expression group." (PMID 34194536, 2021). "These pathways where the coexpressed genes are highly enriched may have a great influence on the development of colon cancer, and GABRD may be regulated by these pathways or participate in the regulation of these pathways." (PMID 34194536, 2021). "Therefore, this study chose to explore GABRD in colon cancer." (PMID 34194536, 2021). "For example, GABRD, a subunit of the GABAA receptor, promotes proliferation and predicts poor prognosis in colon cancer." (PMID 38886975, 2024). "The data of colon cancer patients from The Cancer Genome Atlas (TCGA), CPTAC, and other datasets were used to analyze the expression of GABRD." (PMID 34194536, 2021). "Genes coexpressed with GABRD in colon cancer showed an enrichment for breast cancer and HPV infection pathway, hinting at a possible regulatory role for the monotonic expression of GABRD." (PMID 41048341, 2025). "While we did not see any significant change in the expression of GABRD in our mouse model of colon cancer, our study concluded at the point of adenoma formation, with changes in expression potentially occurring later in the tumorigenic process." (PMID 38886975, 2024). "In order to further investigate the changes in GABRD expression in colon cancer, UALCAN was applied to analyze the colon cancer patients in the TCGA-COAD dataset, and the result also suggested that GABRD expression in cancer tissue was high compared with that in normal tissue." (PMID 34194536, 2021). "However, irrespective of whether expression of GABAA or GABAB receptor subunits were altered in colon cancer, expression of particular receptor subtypes (GABRA1, GABRA5, GABRD, GABRE, GABRG1, GABRG3, GABBR1, and GABBR2) was significantly associated with poor clinical outcome." (PMID 38886975, 2024).
colorectal cancer (6 papers, 2020 to 2024). A primary or metastatic malignant neoplasm that affects the colon or rectum. "In addition, GABRD expression is significantly associated with poor prognosis in patients with colorectal cancer and colon adenocarcinoma." (PMID 35706026, 2022). "A clinical study suggested that GABRD promoted progression and predicted poor prognosis in colorectal cancer." (PMID 35967794, 2022). "We analyzed multiple colorectal cancer datasets with the Oncomine database and found that GABRD was prominently overexpressed in most of the cancer tissue in the datasets (p < 0.05)." (PMID 34194536, 2021). "Little is known about the functional roles of gamma-aminobutyric acid type A receptor subunit delta (GABRD) in colorectal cancer (CRC)." (PMID 33336074, 2020). "A model for the early-stage screening of colorectal cancer was created using seven consensus biomarkers (namely ESM1, DHRS7C, OTOP3, AADACL2, LPHN3, GABRD, and LPAR1), and yielded >98% balanced accuracy on external validation." (PMID 39484215, 2024).
breast carcinoma (5 papers, 2021 to 2025). "Meanwhile, higher GABRD expression in lymph node positive metastases of breast cancer patients was significantly correlated with poor prognosis." (PMID 36923530, 2023). "The delta subunit GABRD is necessary for the GPT2/GABA-induced breast cancer metastasis in xenograft and transgenic mouse models." (PMID 36923530, 2023). "The result of KEGG enrichment analysis suggested that the coexpressed genes of GABRD were significantly involved in breast cancer, human papillomavirus infection, Notch signaling pathway, and other pathways." (PMID 34194536, 2021). "Moreover, GABRD depletion inhibited GPT2-induced breast cancer cell migration." (PMID 36923530, 2023). "We found that the seven GABAA receptor subunits were upregulated in TNBC breast cancers, including GABRA1, GABRA5, GABRD, GABRE, GABRP, GABRQ, and GABRG3." (PMID 36923530, 2023).
colon adenocarcinoma (5 papers, 2020 to 2025). "This upregulation has been associated with poorer survival outcomes in colon adenocarcinoma, and GABRD is an independent prognostic factor." (PMID 40145254, 2025). "We characterized the potential mechanism of GABRD’s activities in CRC using a Gene Set Enrichment Analysis (GSEA) with The Cancer Genome Atlas Colon Adenocarcinoma (TCGA-COAD) dataset." (PMID 33336074, 2020). "Ling Yan and colleagues showed that overexpression of GABRA2, GABRA3, GABRB3, GABRG2, GABRG3, GABRD, and GABRE might be diagnostic for colon adenocarcinoma." (PMID 35565356, 2022). "We investigated the correlation between GABRD expression and patient survival with a tissue microarray by immunohistochemistry (IHC) and validated the result with the combined TCGA-colon adenocarcinoma (COAD) and rectal adenocarcinoma (READ) dataset." (PMID 33336074, 2020).